GHRH (growth hormone releasing hormone)
Diseases named in the same sentence as GHRH in open-access papers (continued):
Sharing a sentence is not in itself a finding about the gene and the disease.
pituitary tumor (12 papers, 2008 to 2025). A benign or malignant neoplasm affecting the pituitary gland. "These so-called ectopic forms arise from either excessive GHRH production or, more rarely, direct GH secretion by an extra-pituitary tumor." (PMID 41573472, 2025). "The remaining causes are due to the occurrence of hypothalamic lesions, or non-pituitary tumors (i.e., NETs) secreting GH or GHRH." (PMID 35456261, 2022). "Early preclinical studies showed that the combination of SST2- and SST5-preferential agonists can act synergistically in the inhibition of GH secretion in both GHRH-stimulated human fetal pituitary cells, as well as in somatomammotroph pituitary tumor cells." (PMID 33920241, 2021). "The effect of GHRH antagonists was further examined on hormone secretion in pituitary tumor cells." (PMID 34439107, 2021). "Therefore, it will be intriguing, in future studies, to gain a greater understanding of the antitumor role of GHRH antagonists in pituitary tumors different from GH-PAs." (PMID 34439107, 2021). "Gigantism associated with MEN1 mutation occurs in approximately 1% of cases, this could be due to a pituitary tumour or, rarely, due to a GHRH-secreting pancreas tumour." (PMID 33805450, 2021). "Freshly dispersed pituitary tumor cells were cultured for a few hours and then loaded with fura-2/AM and subjected to calcium imaging to monitor Ca2+ responses induced by the four classic HRHs perfused sequentially (CRH, LHRH, TRH, and GHRH)." (PMID 26106585, 2015). "We showed that in rat pituitary tumour cells, butyrate enhances hGH release in both not-stimulated and GHRH-stimulated conditions through the activation of GPR41 and 43 receptors." (PMID 25310566, 2014). "Notably, none of the bIGF1RKO+/− animals over 130 wk of age showed pituitary tumors or hyperplasia, whereas 20% of the controls did, most probably a consequence of lifelong GHRH stimulation." (PMID 18959478, 2008).
Anxiety (10 papers, 2012 to 2025). Intense feelings of nervousness, tension, or panic often arise in response to interpersonal stresses. "We previously demonstrated that GHRH deficiency induces a reduction in anxiety- and depression-related behavior in male mice, as well as decreased norepinephrine levels in the striatum area with respect to control animals." (PMID 37998350, 2023). "Anxiety symptoms commonly occur in adolescent females, leading to an increased risk in psychosocial functioning, and there are few studies on emotional behaviors and cognitive functions in female GHRH-KO mice." (PMID 36672612, 2022). "Several synthetic bioactive peptides related to urocortin 3, growth hormone-releasing hormone, neuromedin U, and kisspeptin, have antidepressant-like or anxiety-like effects via the receptors for neurotransmitters or the release of neurotransmitters." (PMID 35203663, 2022). "The increased amount of time spent in the open arms of the EZM implied a lower anxiety phenotype in GHRH-KO females, which is consistence with the GHRH-KO males." (PMID 36672612, 2022). "In a similar fashion, the GHRH antagonist, MZ-4-71, improved memory consolidation in passive avoidance learning, decreased anxiety, and proved to be antidepressive, in CFLP mice treated with amyloid-β25-35." (PMID 23211425, 2012). "Here, we found that growth hormone-releasing hormone knockout (GHRH-KO) mice, a GH-deficiency mouse model characterized by extended lifespan and enhanced insulin sensitivity, showed a lower anxiety symptom and impairment of short-term object recognition memory and autism-like behaviors." (PMID 36672612, 2022). "In addition, a GHRH agonist, JI-34, was found to induce anxiety and depression whereas MZ-4-71, a GHRH antagonist, elicited anxiolytic and anti-depressant effects." (PMID 31959947, 2020). "GHRH KO mice display anxiety and depression-related behaviors." (PMID 25386163, 2014). "In addition, the GHRH agonist, JI-34, induces anxiety and depression whereas the GHRH antagonist, MZ-4-71, elicits anxiolytic and anti-depressant effects." (PMID 25386163, 2014). "L-serine reduced the measures of anxiety in the open field in wild-type and growth hormone-releasing hormone-knockout mice and mitigated cognitive impairments in the novel object-recognition test and sociability in growth hormone-releasing hormone-knockout mice." (PMID 38260101, 2023). "Furthermore, a recent study has shown that male GHRH-/- mice have reduced anxiety, indicating that activation of hypothalamic GH receptors might also be responsible for the behavioural phenotype in Nestin-Cre mice." (PMID 26275221, 2015). "We evaluated the efficacy of the GHRH antagonist analog, MIA-690, against cognitive impairment and anxiety-like behavior in GWI." (PMID 40943436, 2025).
breast carcinoma (10 papers, 2008 to 2025). "Several reports have detailed the effects of treatment with GHRH antagonists on the growth of breast cancers." (PMID 25593995, 2014). "MCF-7 breast cancer cells were also transfected with siRNA for knocking down the GHRH gene." (PMID 18506184, 2008). "Therefore, some authors studied the effect of GHRH antagonists on cell adhesion, observing a 34% reduction compared to control following treatment with MIA-602 in breast cancer, glioblastoma, and ovarian cancer cells." (PMID 39456984, 2024). "The proliferation rate of the MCF-7 breast cancer cell line was not influenced by the presence of the GHRH or its antagonists, since MCF-7 does not express specific receptors for GHRH." (PMID 18506184, 2008). "The GHRH did not affect the proliferation rate of MCF-7 breast cancer cell line, which was also transfected with siRNA for GHRH." (PMID 18506184, 2008).
Cognitive impairment (10 papers, 2016 to 2025). Abnormal cognition is characterized by deficits in thinking, reasoning, or remembering. "Further preclinical studies are needed to discern the beneficial effect of GHRH-GH-IGF axis modulation on cognitive deficits and anxiolytic activity in GWI." (PMID 40943436, 2025). "More information has been obtained on hormonal resistance classically involved in PHP (PTH, TSH, GHRH and GnRH) and on cognitive impairment, while a few data has been collected on bone mineral status, calcitonin levels and glucolipid metabolism." (PMID 33663571, 2021). "Besides, an RCT showed that GHRH administration in healthy elderly and in adults with a mild cognitive impairment had favorable effects on cognition." (PMID 27852283, 2016). "This pre-clinical study aims to evaluate the beneficial effects of the biologically active synthetic GHRH antagonistic analog, MIA-690, on cognitive impairment in an animal model of GWI." (PMID 40943436, 2025). "The administration of growth hormone-releasing hormone (GHRH), an inducer of IGF-1, has been clinically confirmed to ameliorate cognitive impairment by increasing levels of N-acetylaspartyl-glutamate (NAAG) and GABA in AD patients." (PMID 36983803, 2023). "In human studies, treatment with growth hormone-releasing hormone increased NAAG levels in the prefrontal cortex and improved performance of subjects exhibiting mild cognitive impairment." (PMID 28285415, 2017). "In a phase 2 clinical trial, it was found that systemic administration of growth hormone-releasing hormone (GHRH), present in the blood of young individuals, appears to beneficially affect cognitive function in healthy older humans and adults with mild cognitive impairment (MCI)." (PMID 39607636, 2024). "The study demonstrated a favorable effect of GHRH administration in adult patients with mild cognitive impairment, independent of the IGF-1 level that did not change significantly." (PMID 29149058, 2017).
benign prostatic hyperplasia (7 papers, 2012 to 2025). A non-cancerous nodular enlargement of the prostate gland. "It has been described that GHRH antagonists also reduce the expression of PCNA in benign prostatic hyperplasia, breast and cervical cancer and non-small cell lung carcinoma cells." (PMID 27448980, 2016). "In addition, NF-kB/p65 and COX-2 were found reduced by GHRH antagonists, along with a decrease in prostate weight, in experimental benign prostate hyperplasia." (PMID 36232554, 2022). "Recent research underscores the crucial role of hormone regulation in benign prostatic hyperplasia (BPH) and the therapeutic promise of growth hormone-releasing hormone (GH-RH) antagonists." (PMID 40410203, 2025). "GHRH antagonists also reduced prostate size and expression of inflammatory mediators, such as IL-1β, NF-κB p65, and COX-2, in rat prostatic hyperplasia." (PMID 37649486, 2023).
dwarfism (7 papers, 2011 to 2021). "The hypothalamic levels of GH-releasing hormone (GHRH), an important stimulator of somatotroph proliferation, were strongly decreased, which causes somatotroph hypoplasia, dwarfism, and anorexia in mice." (PMID 32722439, 2020). "Dlx1/2-deficient mice show a loss-of-GHRH-neurons and an increase of AgRP-neurons, and consistently develop dwarfism and consume less energy." (PMID 29795232, 2018). "Together, our study revealed that the deficiency of Mll4-directed epigenetic control of GHRH-neuronal genes results in a severe reduction of GHRH neurons and dwarfism in the mouse, providing crucial insights into the molecular etiology underlying dwarfism in human KS patients." (PMID 33431871, 2021). "Our results suggest that the developmental dysregulation of Mll4-directed epigenetic control of transcription plays a role in the development of GHRH-neurons and dwarfism phenotype in mice." (PMID 33431871, 2021). "Further studies are needed to elucidate the role of DAT ablation on the regulation and possible depression of hypohpyseal growth hormone-releasing hormone and the consequent the dwarfism that DAT-/- rats also exhibit." (PMID 32486390, 2020). "Our finding that Dlx1/2cKO mice show dwarfism, an absence of GHRH-neurons, and dysregulated GH signaling establish Dlx1/2 as essential players in the gene network directing the development of GHRH-neurons." (PMID 29795232, 2018). "Growth hormone-releasing hormone (GHRH) is a hypothalamic peptide responsible for stimulating growth hormone release and disruption of the peptide–receptor pair often results in abnormal growth, such as dwarfism or gigantism." (PMID 23316183, 2012). "However, in contrast to our model, exon 1 deletion mice were not obese and exhibited dwarfism possibly due to defects in hypothalamic growth hormone-releasing hormone (GHRH)." (PMID 31974728, 2020).
Insulin resistance (7 papers, 2006 to 2024). Increased resistance towards insulin, that is, diminished effectiveness of insulin in reducing blood glucose levels. "The aim of the present study was to evaluate the relationship between GHRH-induced GH secretion in obese premenopausal women and cardiovascular risk markers or insulin resistance.Premenopausal obese women, aged 35–52 years, were studied." (PMID 20150954, 2010). "The aim of the present study was to evaluate the relationship between GHRH-induced GH secretion in obese premenopausal women and cardiovascular risk markers or insulin resistance." (PMID 20150954, 2010). "Moreover, we report a strong inverse association of GH peak after stimulation with GHRH and the insulin resistance indices, HOMA-IR." (PMID 20150954, 2010). "GHRH/GH signaling is crucial in modulating insulin sensitivity as reduced GH levels due to impaired GHRH activity can exacerbate insulin resistance, contributing to the development of type 2 diabetes." (PMID 39560873, 2024). "Hyperinsulinemia have a direct inhibitory effect on GH secretion, and more severe insulin resistance may impair Growth Hormone Releasing Hormone (GHRH) and the arginine-induced GH response in a population of adults aged 50–9011." (PMID 29785038, 2018). "Furthermore, the lower score of homeostasis model-assessment of insulin resistance (HOMA-IR) indicated that GHRH-KO mice had enhanced insulin sensitivity." (PMID 24175087, 2013). "Insulin can directly suppress GH secretion from the pituitary, while more severe insulin resistance may impair GHRH and the arginine-induced GH response in NAFLD patients." (PMID 22952901, 2012).
pheochromocytoma (7 papers, 2014 to 2025). "A similar case has now been described in a patient with germline MAX mutation and multiple tumours including a GHRH-positive phaeochromocytoma." (PMID 33543431, 2021). "If this occurs, co-secretion of GHRH from the phaeochromocytoma or the presence of underlying genetic abnormalities must be considered." (PMID 24897038, 2014). "An endocrine rather than genetic association occurs when pheochromocytomas secrete hypothalamic-releasing hormones (GHRH or CRH) mimicking the PA and pheo/PGL syndrome, described previously in eight cases." (PMID 25494863, 2015). "For example, cortisol excess caused by adrenocorticotrophic hormone (ACTH) or corticotrophin releasing hormone (CRH) secretion by phaeochromocytoma has been described as has symptomatic vasoactive intestinal peptide (VIP) and growth hormone-releasing hormone (GHRH) secretion." (PMID 37761307, 2023). "A recent series of such cases have been reported in France: 21 patients were identified with ectopic secretion of GHRH, 12 cases were secondary to pancreatic lesions and seven bronchial, and there were no phaeochromocytoma cases." (PMID 24897038, 2014).
endometriosis (6 papers, 2013 to 2025). The growth of functional endometrial tissue in anatomic sites outside the uterine body. "For instance, treatments for endometriosis include danazol, oral contraceptives, and growth hormone-releasing hormone agonists." (PMID 41357576, 2025). "The present study aims to explore the significance of the expression ofgrowth hormone-releasing hormone (GHRH) and its receptor splice variant 1 (GHRHSV1)in endometriosis (EM)." (PMID 24520461, 2013). "Treatment of endometriosis is a difficult matter.The finding on GHRH and SV1 will represent anew approach." (PMID 24520461, 2013). "The expressions of growth hormone-releasing hormone (GHRH) and GHRH-SV1 (splice variant 1 SV1) were markeredly increased in the eutopic endometrium and ectopic lesions compared with normal endometrium, and were higher in advanced (stages III-IV) than in early (stage I-II) endometriosis." (PMID 41301454, 2025). "Thus, it was suggested that GHRH may promote endometrial proliferation and be involved in the pathogenesis of EC and endometriosis." (PMID 35566020, 2022). "GHRH and GHRH-SV1 expression levels differ significantly at differentstages of endometriosis." (PMID 24520461, 2013).
Hyperglycemia (6 papers, 2017 to 2024). An increased concentration of glucose in the blood. "Hyperglycemia appears to directly affect the pituitary somatotrophs, reducing the GH release in response to GHRH or increasing the release of somatostatin." (PMID 33586392, 2021). "During the subsequent studies in rat models in vivo, it was determined that both acute hypo-and hyperglycemia stimulate somatostatin mRNA, whereas GHRH mRNA is stimulated only by hyperglycemia." (PMID 33586392, 2021). "2DG treatment resulted in hyperglycemia, and osmotic changes with hyperglycemia contribute to glucose sensing in β cells, so hyperglycemia and osmotic changes may lead to greater GHRH neuron activation with 2DG treatment." (PMID 33148883, 2020). "Together, these findings suggest insulin or peripheral hyperglycemia may have effects on SST neurons and pituitary somatotrophs to control GH release in addition to the effects of low glucose on GHRH neurons." (PMID 33148883, 2020). "Differences in the SST inputs into GHRH neurons and plasma GH responses between 2DG and insulin suggest these responses may be related to effects of insulin or peripheral hyperglycemia rather than glucose deprivation." (PMID 33148883, 2020).
lipodystrophy (6 papers, 2007 to 2024). A congenital or acquired disorder characterized by abnormal loss or redistribution of the adipose tissue in the body. "There are treatments for lipodystrophy, including tesamorelin, a synthetic growth hormone-releasing hormone (GHRH) approved by the Food and Drug Administration (FDA) for reduction of VAT." (PMID 36845310, 2023). "Among the lipodystrophy patients, the peak GH response to GHRH-arginine was significantly predicted by VAT (P = 0.008), FFA (P = 0.04) and insulin level (P = 0.007) in regression modeling." (PMID 17597538, 2007). "The addition of arginine to GHRH in the lipodystrophy patients led to a 247% greater increase in GH secretion compared to the lipodystrophy patients who received only GHRH." (PMID 17597538, 2007). "The data demonstrated GH deficiency in 18% of the lipodystrophy group vs 5.9% of the non-lipodystrophy group and 0% of the comparison group, using the stringent criterion of 3.3 ng/ml for peak GH response to GHRH-arginine." (PMID 17597538, 2007). "Tesamorelin (Theratechnologies, Inc., Montreal, Quebec, Canada) is a synthetic analog of human growth hormone-releasing factor (also known as growth hormone-releasing hormone, GHRH), which is indicated for the treatment of excess abdominal fat in HIV-infected patients with lipodystrophy." (PMID 26457580, 2015). "Koutkia and colleagues compared the difference in GH release by GHRH+arginine stimulation with GHRH alone in 13 HIV-infected men with lipodystrophy and 10 HIV-infected men without lipodystrophy after an overnight fast." (PMID 17597538, 2007).